MTOR (mechanistic target of rapamycin kinase)
Diseases named in the same sentence as MTOR in open-access papers (continued):
Sharing a sentence is not in itself a finding about the gene and the disease.
acute myeloid leukemia (continued). "In acute myeloid leukemia (AML) cells, emodin-induced apoptosis was associated with the suppression of the PI3K/Akt/mTOR cell signaling." (PMID 34068184, 2021). "Aberrant activation of the PI3K/AKT/mTOR axis, which deregulates cellular functions such as proliferation, metabolism, and survival, has been associated with the progression and pathogenesis of a broad spectrum of various types of human cancer, including AML (acute myeloid leukaemia)." (PMID 34044827, 2021). "Therefore, we hypothesized that deoxyshikonin inhibited viability and glycolysis, suppressing pyruvate kinase M2 via the Akt/mTOR pathway in acute myeloid leukemia cells." (PMID 32850379, 2020). "Among blood system tumors, the overexpression of Tim3 on leukemic stem cells in acute myeloid leukemia (AML) can activate PI3K/AKT/mTOR and NF-κB signaling pathways." (PMID 33330064, 2020). "AZD1208 inhibits growth of acute myeloid leukemia (AML) cells, in part through inhibition of mTOR, S6K, S6 and 4E-BP1." (PMID 30654529, 2019). "The PI3K/AKT/mTOR pathway is known to promote cell survival through translational control of Mcl-1 in acute myeloid leukemia (AML)." (PMID 31121982, 2019). "For example, activated tyrosine kinase SRC interacts with motifs on Akt-mTOR in acute myeloid leukemia (AML) cells, a process which upregulates signaling and stemness in AML." (PMID 29518044, 2018). "The LKB1/AMPK/mTOR axis functions in hematopoietic cancers, such as acute myeloid leukemia (AML) and acute lymphoblastic leukemia (ALL); consequently, metformin represents a new perspective in hematological cancer therapy." (PMID 30208162, 2018). "We have recently shown that the dual PI3K/mTOR inhibitor PKI-587 can inhibit the growth of acute myeloid leukemia (AML) as well as acute lymphoblastic leukemia (ALL) cell lines both in vitro and in vivo." (PMID 29951132, 2018). "In alignment with our findings, sunitinib was active against acute myeloid leukemias (AML) possessing activating PDGFR, FLT-3, and c-kit mutations through inhibiting mTOR and reducing Mcl-1 levels." (PMID 29066973, 2017). "Mammalian target of rapamycin (mTOR) signaling is a critical pathway in the biology of acute myeloid leukemia (AML)." (PMID 26473447, 2015). "In acute myeloid leukemia (AML), activation of the Ras/Raf/MEK/ERK and Ras/PI3K/Akt/mTOR pathway can result from mutated upstream targets such as class III RTKs." (PMID 21422497, 2011). "Here we show that the mTOR effectors, 4EBP1, p70S6K and rpS6, are highly activated in cultured and primary FLT3-mutated acute myeloid leukemia (AML) cells." (PMID 21067588, 2010). "In acute myeloid leukemia (AML), prazosin inhibited viability and induced cell cycle arrest in U937 and HL60 cell lines, reducing phosphorylated Akt (p-Akt) and mTOR (p-mTOR)." (PMID 40906372, 2025). "In the U937 and HL60 acute myeloid leukemia cell lines, it activates the PI3K/Akt/mTOR signaling pathway, and its knockdown suppresses proliferation." (PMID 40906372, 2025). "Linc00239 is also overexpressed in acute myeloid leukemia cells and promotes oncogenic behavior by regulating PI3K/AKT/mTOR signaling." (PMID 38850457, 2025). "TNS1 knockdown also diminished proliferation in SW620 colon cancer cells and suppressed the PI3K/Akt/mTOR pathway, decreasing proliferation in U937 and HL60 acute myeloid leukemia cells." (PMID 40906372, 2025). "In acute myeloid leukemia, circ-PAN3 promotes drug resistance by inducing autophagy through modulating AMPK/mTOR pathway." (PMID 39866238, 2025). "Propofol inhibited the differentiation capacity of acute myeloid leukaemia stem cells (CD34+/CD38− subsets)In presence of Propofol, the activity of Akt/mTOR, and the Wnt/β‐catenin pathways were diminished." (PMID 37156724, 2023). "Evidence suggested that the immunosuppressive effects driven by acute myeloid leukemia (AML) cells involve interactions between TIM-3 and GAL-9 through protein kinase C (PKC)/mTOR pathways." (PMID 37898403, 2023).
acute myeloid leukemia (continued). "The influence of mTOR has also been discussed in chronic myeloid leukemia (CML) and acute myeloid leukemia (AML)." (PMID 36980552, 2023). "Here, we show that acute myeloid leukemia cell lines benefit from an important inter-play between mTORC1-ERK and AKT, explaining why mTOR inhibition is rather ineffective in killing those cells." (PMID 37237490, 2023). "By promoting autophagy and apoptosis mediated by mTOR, metformin sensitizes FLT3-ITD-positive acute myeloid leukemia to sorafenib." (PMID 37842232, 2023). "In acute myeloid leukaemia, LKB1/AMPK signalling pathway has tumour suppressive activity by inhibiting mTOR‐dependent oncogenic mRNA translation." (PMID 35106915, 2022). "SNX20 participates mainly in the acute myeloid leukemia, NOD-like receptor signaling pathway, the mTOR signaling pathway." (PMID 35771139, 2022). "By also suppressing the Akt-mTOR pathway, DSK has been shown to counteract the viability and glycolysis of acute myeloid leukemia cells." (PMID 35806120, 2022). "When it comes to acute myelocytic leukemia (AML), more than half of the patients are identified with the same disorder of PI3K/Akt/mTOR axis, which contributes to the decreased long-term survival." (PMID 34691211, 2021). "Meanwhile, circPAN3 was reported as a key mediator of drug resistance in acute myeloid leukemia by regulating autophagy and the AMP-activated protein kinase/ mammalian target of rapamycin (AMPK/mTOR) signaling pathway." (PMID 33436088, 2021). "Interestingly, alterations in both PLCβ1 and PI3K/Akt/mTOR pathways have been associated with myelodysplastic syndromes (MDS) and acute myeloid leukemia (AML)." (PMID 32276377, 2020). "For example, in acute myeloid leukemia, CYT997 killed acute myeloid leukemia cells via activation of caspases and inhibition of PI3K/Akt/mTOR pathway." (PMID 32576206, 2020). "Abnormal activation of the PI3K/AKT/mTOR pathway helps tumors to produce MDR, such as acute myeloid leukemia (AML) and ovarian cancer." (PMID 32973135, 2020). "mRNA expression levels of VEGFC (contrary to other VEGFs isoform), PI3K, AKT, mTOR, MEK1, PTEN,IL6, LC3 and P62 genes were upregulated in acute myeloid leukemia (AML) cells following treatment with ATO/THAL." (PMID 31721534, 2020). "In acute myeloid leukemia (AML), mTOR-mediated up-regulation of PFKFB3 is essential for cell survival, as mTORC1 up-regulates PFKFB3 in a HIF1α-dependent manner, and PFKFB3 silencing suppresses glycolysis and cell proliferation and activates apoptosis." (PMID 30234009, 2018). "PFKFB3 also plays an important role in the survival of acute myeloid leukemia (AML) cells, as PFKFB3 is a novel downstream substrate of the mTOR (mechanistic target of rapamycin) signaling pathway." (PMID 28977989, 2017). "Inhibitor of mTOR WYE-354, and pan RTK inhibitor sunitinib synergistically inhibit acute myeloid leukemia cell lines K562 and HL60." (PMID 27454254, 2016). "mTOR activation leads to enhanced survival signaling in acute myeloid leukemia (AML) cells." (PMID 27391151, 2016). "Here we report for the first time that caffeine inhibits the activation of mTOR in THP-1 human myeloid leukaemia cells, primary human acute myeloid leukaemia (AML) cells and primary human basophils." (PMID 26384306, 2015). "Signaling through the phosphatidylinositol 3-kinase (PI3K) pathway and its downstream effectors, Akt and mechanistic target of rapamycin (mTOR), is aberrantly activated in acute myeloid leukemia (AML) patients, where it contributes to leukemic cell proliferation, survival, and drug-resistance." (PMID 23271044, 2012). "Abnormalities within PI-PLCβ1 and the PI3K/Akt/mTOR pathway have been linked to myelodysplastic syndrome (MDS), a pathological condition characterized by hematopoietic stem cell mutations, amongst which 30% of MDS patients were found to progress to acute myeloid leukemia (AML)." (PMID 40572742, 2025).
acute myeloid leukemia (continued). "This is in agreement with a previous study on acute myeloid leukemia on the interplay between G6PD inhibition and mTORC1 activity, since mTOR is a conserved serine/threonine kinase controlling cell growth and metabolism in response to nutrients, growth factors, cellular energy, and stress." (PMID 36271440, 2022). "However, it is reported that the activation of mTOR signal in acute myeloid leukemia (AML) cells could promote the accumulation of ROS, and ultimately lead to cell iron death." (PMID 34745435, 2021). "Similarly, the simultaneous inhibition of phosphoinositide 3-kinase (PI3K) and a mechanistic target of rapamycin kinase (mTOR) was reported to activate extracellular signal-regulated kinase (ERK), a pro-survival factor, in acute myeloid leukemia." (PMID 31861937, 2019). "Therapeutic targeting of PI3K-Akt-mTOR is considered a possible strategy in human acute myeloid leukaemia (AML); the most important rationale being the proapoptotic and antiproliferative effects of direct PI3K/mTOR inhibition observed in experimental studies of human AML cells." (PMID 27845732, 2016). "Finally, the activation interaction between mTOR and RPS6KB1 in the ‘acute myeloid leukemia’ pathway was predicted to be of phosphorylation type by our method." (PMID 24625764, 2014). "In acute myeloid leukemia (AML), activation of phosphatidylinositol-3-kinase (PI3K)/Akt and mammalian target of rapamycin (mTOR) signaling pathways leads to enhanced glycolysis and increased production of reactive oxygen species (ROS) in myeloblasts." (PMID 38396817, 2024). "Bone marrow (BM) microenvironment substantially limits downregulation of mTOR and MYC pathway in FLT3-ITD acute myeloid leukemia (AML) cells upon FLT3 inhibition in vitro and in vivo." (PMID 36259537, 2022). "Interestingly, they found that resistance to PI3K/mTOR inhibition correlated with a fair number of PKC sites, leading to the conclusion that acute myeloid leukemia-derived cell lines use PKC pathways to proliferate, thus explaining the resistance to PI3K/mTOR inhibition." (PMID 28848546, 2017). "In both acute myeloid leukemia (AML) mouse model and AML cell lines including MOLM-13 and THP1, PD-L1 boosts glycolytic metabolism, which enhances cell proliferation and tumor formation via the Akt/mTOR/HIF-1α signaling pathway." (PMID 35907881, 2022).
neuroblastoma (173 papers, 2009 to 2026). Neuroblastoma (NB) is the most common solid, extracranial childhood tumor. "Complementing conventional chemotherapy treatment with PIM/PI3K/mTOR inhibition has the potential to improve clinical outcomes and reduce severe late effects in children with high‐risk neuroblastoma." (PMID 31310053, 2019). "The combination of crizotinib with a selective mTOR inhibitor has been recently described in ALK-mutated neuroblastoma and NSCLC." (PMID 27662658, 2016). "Indeed, Hcy metabolites inhibit autophagy, elevate Aβ, and induce neuropathy by dysregulating the Phf8/H4K20me1-dependent epigenetic regulation of mTOR in cystathionine β-synthase-deficient mice and Cbs-silenced mouse neuroblastoma cells." (PMID 39125665, 2024). "Notably, Pon1 depletion caused changes in the Phf8- > H4K20me1- > mTOR- > autophagy pathway akin to the changes induced by HHcy in the mouse brain and neuroblastoma cells." (PMID 36899882, 2023). "Activation of insulin signalling activation may also be implicated in the promotion of mTOR-independent autophagic clearance of poly(Q) aggregates in N2a mouse neuroblastoma cells." (PMID 33739284, 2021). "Another study revealed that the treatment of neuroblastoma cells with honokiol caused significant downregulation of mTOR phosphorylation, which leads to the induction of autophagy of neuroblastoma cells (neuro-2a cells) through the PI3K/Akt/mTOR signalling pathways." (PMID 31877856, 2019). "On the other hand, mTOR is a master regulator of protein synthesis that controls cell proliferation and metabolism, and frequently over-activation and dysregulation of the mTOR pathway has been implicated in neuroblastoma pathogenesis." (PMID 26687764, 2015). "To elucidate the mechanism by which Blmh depletion impacts Phf8 and its downstream effects on mTOR, autophagy, and AβPP, we first examined whether our findings in Blmh-/- mice can be recapitulated in cultured mouse neuroblastoma N2a-APPswe cells carrying a mutated human AβPP transgene." (PMID 37718819, 2023). "Thus, MYCN might have enhanced S6K phosphorylation by activating the mTOR pathway in neuroblastomas caused in the double transgenic mice." (PMID 24391509, 2014). "INSM2 mediates the lipid metabolism SREBP1expression via the mTOR signaling pathway, which further interferes with lipid metabolism in neuroblastoma." (PMID 40636521, 2025). "Strong phosphorylation of the S6 ribosomal protein (a target of mTOR) was also observed in neuroblastoma samples; therefore, the PI3/Akt/mTOR pathway affects several pathways or proteins promoting a more aggressive cancer cell phenotype." (PMID 40104501, 2025). "Among participants achieving CR, all received combination therapy (mTOR inhibitor with chemotherapy in rhabdomyosarcoma with PI3K or FGFR4 gain-of-function mutations; irinotecan combination therapy in neuroblastoma with an ATRX mutation)." (PMID 38755180, 2024). "Combinations of MEK inhibitors with inhibitors of the PI3 kinase/AKT/mTOR pathway are also effective in preclinical models of neuroblastoma." (PMID 39001383, 2024). "An increase in the mTOR mRNA expression was also noted in a human undifferentiated neuroblastoma (SH-SY5Y) cell line after VGVAPG peptide stimulation." (PMID 38967692, 2024). "In turn, shRNA-mediated DDX1 knockdown in DDX1-MYCN coamplified neuroblastoma cells resulted in reduced phosphorylation of mTOR and P70-S6K." (PMID 38197697, 2024). "The depletion of Pon1 increased H4K20me1 binding to the mTOR promoter, demonstrated in mouse neuroblastoma N2a-APPswe cells, and upregulated mTOR signaling, which in turn inhibited the autophagy flux." (PMID 39125665, 2024).
neuroblastoma (continued). "The mammalian target of rapamycin (mTOR) pathway promotes neuroblastoma cell survival and chemoresistance." (PMID 37479876, 2023). "Previous studies have demonstrated mTOR pathway activation in two thirds of neuroblastoma patients, with AKT and mTOR phosphorylation in primary neuroblastoma, and this pathway activation correlated with reduced event-free and overall survival." (PMID 35490242, 2022). "Different studies showed the role of the phosphatidylinositol 3-kinase (PI3K)/mTOR pathway in neuroblastoma." (PMID 36139583, 2022). "We have previously shown that PI3K/mTOR inhibitors kill MYCN-amplified neuroblastoma cells and have the ability to eliminate MYCN protein in vivo." (PMID 34522028, 2022). "Rapamycin inhibits mTOR and induces autophagy, and rapamycin induces growth arrest in neuroblastoma cells, suggesting a growth inhibitory role for autophagy in neuroblastoma." (PMID 36267982, 2022). "AMPK stimulates the formation of autophagosomes by inhibiting mTOR and has been described to reduce the amount of PrPSc in a neuroblastoma cell line persistently with permanent infection." (PMID 36148145, 2022). "In the present study we found that neuroblastoma presented the highest level of mRNA expression of genes involved in the mTOR pathway (small cell lung cancer ranked second) and presented low promoter methylation." (PMID 35490242, 2022). "Morroniside has been shown to activate PI3K/Akt/mTOR signaling in different types of cells, such as osteoblast precursors, granulosa cells, and human neuroblastoma cells." (PMID 36618945, 2022). "We also showed that blocking a single cancer-specific gene (MYCN) is a more sustainable method for inhibiting the mTOR pathway in neuroblastoma cells only, avoiding side effects of mTOR inhibition in healthy cells." (PMID 35490242, 2022). "Findings show that compared with the normal control group, the high expression of PCNP decreased the growth, migration, and invasion of human neuroblastoma through MAPK and PI3K/AKT/mTOR signaling pathways and promoted the apoptosis of neuroblastoma." (PMID 35186732, 2022). "In the neuroblastoma cell line, the E2F-targeted portions of cancer pathways, thermogenesis, mTOR signaling, insulin signaling, and circadian entrainment were all inhibited, as one would expect based on the previous research on E2F1." (PMID 36271102, 2022). "Mechanistically, INSM2 regulates the expression of SREBP1 by regulating the mTOR signaling pathway, which in turn affects lipid metabolism, thereby mediating the occurrence and development of neuroblastoma." (PMID 36114560, 2022). "In summary, we suggest that INSM2 affects the expression of SREBP1 by regulating the mTOR signaling pathway, which in turn affects the lipid metabolism process of neuroblastoma cells." (PMID 36114560, 2022). "In this context, our results provided us with a good reason to investigate autophagy/mTOR as a target to reduce neuroblastoma cell migration." (PMID 35335990, 2022). "We noticed that neuroblastoma patients with high mTOR pathway activity had significantly worse survival outcomes." (PMID 35490242, 2022). "JQ1 has been reported to cause human neuroblastoma cell cycle arrest in G1 phase mainly by inhibiting the MYCN and mTOR signaling pathways." (PMID 35902869, 2022). "Neuroblastoma cell lines presented high expressions for different genes of the mTOR pathway and a higher expression was found in MNA versus non-MNA patients." (PMID 35490242, 2022). "We have previously shown that the PI3K pathway regulates HIF‐2α specifically via mTORC2 and in addition is a promising treatment strategy using a triple PIM/PI3K/mTOR inhibitor in trunk neural crest‐derived tumor form neuroblastoma." (PMID 32940375, 2021). "Enhanced proliferation and metastasis of neuroblastoma cells was observed following DEHP exposure-induced activation of PI3K/Akt/mTOR signaling." (PMID 34208283, 2021).